POU2AF1 (POU class 2 homeobox associating factor 1)
Diseases named in the same sentence as POU2AF1 in open-access papers:
POU2AF1 is named in the same sentence as 62 diseases in open-access papers, as found by Europe PMC text mining. Sharing a sentence is not in itself a finding about the gene and the disease. The quoted sentences say what the papers report.
multiple myeloma (11 papers, 2009 to 2024). "In a POU2AF1-dependent, disseminated murine model of multiple myeloma, AU-24118 enhanced survival compared to pomalidomide, an approved treatment for multiple myeloma." (PMID 38328238, 2024). "Mechanistically, mSWI/SNF ATPase degrader treatment in multiple myeloma cells compacted chromatin, dislodged POU2AF1 and IRF4, and decreased IRF4 signaling." (PMID 38328238, 2024). "In multiple myeloma (MM), four Supertarget genes encode transcription factors such as interferon regulatory factor 4 (IRF4), PR/SET domain 1 (PRDM1), POU class 2 homeobox associating factor 1 (POU2AF1), and myocyte enhancer factor 2C (MEF2C)." (PMID 37297004, 2023). "SuperDendrix also finds associations for three downstream targets of TCF3 and IRF4 transcription factors: BCL2 and {leukemia, myeloma, MEF2B(A)}, PIM2 and myeloma, and POU2AF1 and Myeloma,MEF2BA." (PMID 35382456, 2022). "POU2AF1 helps in the progression of multiple myeloma (MM) when activated by amplification or other mechanisms." (PMID 33336008, 2020). "Growth-promoting effects of overexpressed POU2AF1 have been demonstrated in human multiple myeloma cells from hematological malignancies." (PMID 27835906, 2016). "POU2AF1 amplification has been detected in multiple myeloma cells and this copy number variation also reflected in over-expression at both the mRNA and protein levels." (PMID 22952604, 2012). "Furthermore, our investigations extended to other POU2AF1 complex-dependent B cell malignancies, including multiple myeloma, wherein sensitivity to the mSWI/SNF ATPase PROTAC degrader was observed in vitro and in vivo." (PMID 38328238, 2024). "As a B cell transcriptional coactivator, POU2AF1 regulates the expression of B cell maturation factor TNFRSF17 and stimulates the growth of myeloma cells." (PMID 35517856, 2022). "Dependencies on POU2AF1 and PIM2, the target genes of TCF3 and IRF4 transcription factors, suggest cancer-type-specific addiction to transcriptional regulatory pathway in myeloma." (PMID 35382456, 2022). "Using data from the DepMap Project33,34, we discovered that POU2AF1 is indispensable for the growth of DLBCL and multiple myeloma (MM) cells but is non-essential for other cancer types." (PMID 38328238, 2024).
lymphoma (8 papers, 2009 to 2024). A malignant (clonal) proliferation of B- lymphocytes or T- lymphocytes which involves the lymph nodes, bone marrow and/or extranodal sites. "The functional polymorphism of the POU2AF1 gene 3′-UTR was linked with an increased predisposition to lymphoma." (PMID 36568638, 2022). "Kan Zhai’s study revealed that the gene mutation in 3′-UTR regulates POU2AF1 expression and subsequently gives rise to lymphoma." (PMID 33336008, 2020). "POU2AF1 polymorphism is associated with susceptibility to lymphoma, and mice deficient in POU2AF1 exhibit reduced numbers of mature B cells and defective immune responses to antigens." (PMID 29375549, 2017). "Additionally, a germline variation in the 3′-untranslated region of the POU2AF1 gene was shown to be associated with susceptibility to lymphoma." (PMID 36817488, 2023).
Autoimmunity (6 papers, 2019 to 2025). The occurrence of an immune reaction against the organism's own cells or tissues. "In fact, many genetic variants implicated in autoimmunity exhibit their greatest regulatory potential in GC-associated cellular populations, including BCL6 and transcription factors regulating B cell differentiation, such as POU domain class 2 homeobox associating factor 1 (POU2AF1) and HHEX." (PMID 35887298, 2022).
diffuse large B-cell lymphoma (6 papers, 2019 to 2025). "The OCA-B oncogene is upregulated by BRD4-loaded super-enhancers that interact with POU2AF1 loci and cause the development of diffuse large B-cell lymphoma (DLBCL)." (PMID 37190100, 2023). "Mutations in POU2AF1 might be associated with lower levels of expression, were more frequent in transformed FLs, and seemed to be specific to transformed- compared with de novo-diffuse large B-cell lymphomas." (PMID 30802265, 2019). "Additional examples of tumor self-antigens include lineage-restricted markers such as POU2AF1 in diffuse large B-cell lymphoma, oncoproteins from the CEACAM family in colon cancer, and known differentiation antigens like MLANA/MART1 in melanoma." (PMID 40672284, 2025). "POU2AF1 hypo-methylated probes span a known BRD4-regulated super-enhancer activated in Diffuse Large B Cell Lymphoma." (PMID 34793513, 2021).
Hodgkins lymphoma (5 papers, 2007 to 2022). A heterogeneous group of malignant lymphoid neoplasms of B-cell origin characterized histologically by the presence of Hodgkin and Reed-Sternberg (HRS) cells in the vast majority of cases. "Known diseases associated with POU2AF1 include primary biliary cholangitis, Hodgkin’s lymphoma, and lymphocytic depletion." (PMID 33949290, 2021).
COVID-19 (3 papers, 2023). A disease caused by infection with severe acute respiratory syndrome coronavirus 2. "On the other hand, the Humoral response GO term, reflecting both complement (SERPING1, C1QB) and B cell activation (JCHAIN, POU2AF1), was progressively more enriched in COVID-19 patients from T1 through T3." (PMID 37365222, 2023). "Thus, we think that POU2AF1 might be therapeutic targets for COVID-19-related airway diseases." (PMID 37495990, 2023).
emphysema (3 papers, 2017 to 2022). "POU2AF1 expression correlates with emphysema severity, suggesting a potential contributing role." (PMID 33535173, 2021). "However, the mechanism of POU2AF1 in emphysema needs further research." (PMID 33535173, 2021). "Emphysema patients, but not subjects with bronchiolitis, were associated with enhanced B-cell homing and activation pathways and the expression of genes such as CXCL13, CCL19 and POU2AF1 correlated with emphysema severity." (PMID 35820851, 2022). "We identified a series of significant pathways, including BCR signaling pathway, ECM-related pathways, NF-κB and TGF-β signaling pathways, and several hub genes (i.e. CD19, BLK, MS4A1, POU2AF1, and COL6A1) that may be involved in the emphysema phenotype of COPD." (PMID 33535173, 2021).
leukemia (3 papers, 2009 to 2022). A malignant (clonal) hematologic disorder, involving hematopoietic stem cells and characterized by the presence of primitive or atypical myeloid or lymphoid cells in the bone marrow and the blood. "Six genes were identified in baboons (WNT3, POU2AF1, CCR7, ARG2, CD177, and WLS) and validated in human leukemia patients exposed to radiotherapy." (PMID 33737626, 2021).
multiple sclerosis (3 papers, 2022 to 2025). A progressive autoimmune disorder affecting the central nervous system resulting in demyelination. "Using 2 human multiple sclerosis (MS) datasets, we show that POU2AF1, the gene encoding OCA-B, is elevated in CD4+ T cells from patients with MS." (PMID 40299553, 2025).
rheumatoid arthritis (3 papers, 2021 to 2024). A chronic, systemic autoimmune disorder characterized by inflammation in the synovial membranes and articular surfaces. "Consistent with data from animal studies, Expression of POU2AF1 mRNA was elevated in B from synovial fluid of rheumatoid arthritis patients and was strongly correlated with CD21L, a molecular marker of GCs56." (PMID 34521820, 2021).
allergic asthma (2 papers, 2023 to 2024). A asthma with a basis in a pathological type I hypersensitivity reaction. "Recent studies have shown that IL‐38 could inhibit the activation of intracellular STAT1/3, ERK1/2, P38 MAPK, and NF‐κB signaling pathways, and upregulate the expression of antiallergic response gene RGS13 and host defense‐related gene POU2AF1 in mice with allergic asthma." (PMID 37382260, 2023).
Arthritis (2 papers, 2020 to 2021). Inflammation of a joint. "POU2AF1 was identified when comparing arthritis versus healthy or ACPA + individuals, suggesting that the downregulation of such genes starts after the onset of symptoms in RA patients." (PMID 33004899, 2020). "POU2AF1(Bob1)-sufficient mice lead to abrogated germinal center B cell formation, anti-CII antibody production, and Collagen-induced arthritis development." (PMID 34521820, 2021).
breast carcinoma (2 papers, 2012 to 2020). "Evidence indicates that POU2AF1 is associated with various types of lymphoid malignancies, colorectal cancer, Lynch syndrome, and survival in breast cancer." (PMID 32271791, 2020). "Barcode validation results for differential over-expression of MEF2C, SMAD3 and POU2AF1 within two platforms for several gene-probes in different breast cancer tissues." (PMID 22952604, 2012). "In this paper, we have analyzed the role that thermodynamic fluctuations in energy at the cell-level play in the synthesis of transcription factors MNDA, POU2AF1, MEF2C and SMAD3 and how can this energetic constrains be related with the presence of primary breast carcinomas." (PMID 22952604, 2012).
colon cancer (2 papers, 2010 to 2025). "The 11q23 locus, associated with a gender-independent increased rectal cancer risk and a moderate colonic cancer risk, maps to a 60 kb region on human chromosome 11 containing 3 ORFs (C11orf53, FLJ45803, LOC120376) and a nearby gene involved in humoral immune response, POU2AF1." (PMID 21311099, 2010).
lung fibrosis (2 papers, 2020 to 2024). "Knockout studies have shown that the deletion of POU2AF1 provides protection from bleomycin-induced lung fibrosis in mice, suggesting its pivotal role in IPF pathogenesis." (PMID 39944354, 2024). "A prior study using IPF lungs documented that transcriptome analysis identified POU2AF1 as a promoter of pulmonary fibrosis and it is highly expressed in aggregates of B cells." (PMID 32937976, 2020).
acute myeloid leukemia (1 paper, 2020). Acute myeloid leukemia (AML) is a group of neoplasms arising from precursor cells committed to the myeloid cell-line differentiation. "The co-expression of POU2AF1 and Oct-2 can be a helpful prognosis for patients with acute myeloid leukemia (AML)." (PMID 33336008, 2020).
agammaglobulinemia (1 paper, 2022). "A patient with a mutation in the Pou2af1 gene leading to the absence of BOB.1/OBF.1 protein was described with B cell developmental defects, agammaglobulinemia and a reduction in circulating TFH cells." (PMID 35603192, 2022).
allergic disease (1 paper, 2022). An immune response that occurs following re-exposure to an innocuous antigen, and that requires the presence of existing antibodies against that antigen. "The cross-population meta-analysis identified the ancestry common variant in POU2AF1, which was associated with autoimmune and allergic disease susceptibility." (PMID 35753705, 2022). "The SIK2 locus, located downstream of POU2AF1, was previously reported to associate with allergic diseases." (PMID 35753705, 2022). "Several variants around POU2AF1 had been reported to be associated with the allergic diseases, including BA, PO and AD." (PMID 35753705, 2022). "Our study newly identified six loci associated with allergic diseases (MIIP, CXCR4, SCML4, CYP1B1, ICOS and LINC00824) and four pleiotropic loci associated with both autoimmune and allergic diseases (PRDM2, G3BP1, HBS1L and POU2AF1)." (PMID 35753705, 2022). "We identified four loci shared between the six autoimmune and allergic diseases (rs10803431 at PRDM2, OR=1.07, p=2.3×10−8, rs2053062 at G3BP1, OR=0.90, p=2.9×10−8, rs2210366 at HBS1L, OR=1.07, p=2.5×10−8 in Japanese and rs4529910 at POU2AF1, OR=0.96, p=1.9×10−10 across ancestries)." (PMID 35753705, 2022).
aneurysm (1 paper, 2021). Bulging or ballooning in an area of an artery secondary to arterial wall weakening. "Subsequent immunohistochemistry results also confirmed that POU2AF1 were highly associated with AAA and aneurysm enlargement." (PMID 34637689, 2021).
atherosclerosis (1 paper, 2021). A disease characterized by the build-up of fatty material and calcium deposition in the arterial wall resulting in partial or complete occlusion of the arterial lumen. "It is reported that POU2AF1 participates in the immune and inflammatory reactions associated with atherosclerosis.However, current evidence about the biological function of POU2AF1 in AAA is limited." (PMID 34637689, 2021).
autoimmune liver diseases (1 paper, 2019). "Genetic variants of POU2AF1 were associated with the occurrence of immune-senescence and autoimmune liver diseases." (PMID 31281827, 2019).
chronic lymphocytic leukemia (1 paper, 2020). "Expression dysregulation or POU2AF1 mutation is also related to the development of chronic lymphocytic leukemia (CLL)." (PMID 32012488, 2020).
HIV-1 infection (1 paper, 2005). The type species of lentivirus and the etiologic agent of acquired immunodeficiency syndrome (AIDS). "Several genes have been established as important for HIV-1 infection and replication, including Pou2AF1 (OBF-1), complement factor H related 3, CD4 receptor, ICAM-1, NA, and cyclin A1." (PMID 15780141, 2005).
lung adenocarcinoma (1 paper, 2024). A carcinoma that arises from the lung and is characterized by the presence of malignant glandular epithelial cells. "However, some studies showcase the expression of POU2AF1 in normal human airway epithelium and lung adenocarcinoma tissue." (PMID 39201394, 2024).
metastatic melanoma (1 paper, 2020). A melanoma that has spread from its primary site to another anatomic site. "POU2AF1, which was upregulated in the cutaneous metastatic melanoma, is a B cell-specific coactivator that can stimulate the gene transcription." (PMID 33336008, 2020). "Survival and multivariate Cox regression analyses revealed four vital genes, namely, POU2AF1, ITGAL, CXCR2P1, and MZB1, that affect the prognosis of patients with metastatic melanoma." (PMID 33336008, 2020).
nasopharyngeal carcinoma (1 paper, 2022). A carcinoma arising from the nasopharyngeal epithelium. "(2020) reported top three hub genes of PPI network of FANCI, POSTN, IFIH1, ZMYND10, PACRG and POU2AF1 for nasopharyngeal carcinoma biomarkers using STRING database PPI network construction with MCODE for module analysis." (PMID 36299526, 2022).
nephrolithiasis (1 paper, 2022). The presence of a calculus in the pelvis of the kidney; this is most often composed of mineral salts and proteins. "Finally, the POU2AF1 locus has been associated with both nephrolithiasis and urinary pH which are current areas of interest in feline CKD71–73." (PMID 35115544, 2022).
radiation sickness (1 paper, 2022). "Up-regulation of FDXR and DDB2 GE indicates risk of mild acute radiation sickness, whereas an up-regulation of FDXR and DDB2 combined with a down-regulation of WNT3 and POU2AF1 predicts severe ARS10,11." (PMID 35680903, 2022). "Specific radiation-sensitive genes (such as FDXR, DDB2, WNT3, POU2AF1) have become well established for biodosimetry purposes and acute radiation sickness (ARS)-prediction." (PMID 35680903, 2022).
respiratory failure (1 paper, 2017). The significant impairment of gas exchange within the lungs resulting in hypoxia, hypercarbia, or both, to the extent that organ tissue perfusion is severely compromised. "Given the relationship between POU2AF1, TCL1A, and BLK expression and the development of BOS, we investigated the expression of these three genes in public data sets from blood of patients with other causes of respiratory failure." (PMID 29375549, 2017).
stomach cancer (1 paper, 2022). "As we can see, we obtained five genes with the greatest fold change of expression, among which some, such as POU2AF1 and IYD, can be found in different regions at the same time and may have a pertinent role in leading to the occurrence of gastric cancer." (PMID 36568638, 2022). "As newly discovered gene targets, POU2AF1 and IYD might have a pertinent function in the development of stomach cancer and have yet to be further explored." (PMID 36568638, 2022).
tumor (21 papers, 2014 to 2025). "POU2AF1 is also an important gene in tumorigenesis and tumor progression." (PMID 32012488, 2020). "The identified epigenetic PARPi hallmarks contained hundreds of DMRs; however, only a few DMRs were reported as tumor driver genes (SOX2, POU2AF1, PTK6, VHL, JAK3, and EZH2) or as HRD genes (RAD51C)." (PMID 38927686, 2024). "Notably, some genes (e.g., MET, HSPA6, ID1, MECOM, POU2AF1, SFRP4, CDH1) exhibited expression predominantly in tumor cells and a limited number of other cell types." (PMID 40954493, 2025). "Notably, our findings highlight seven genes (FAM30A, MDM4, POU2AF1, SYNE2, TNFRSF13C, TPTEP2, VAMP1) presenting positive correlations with ESR2 expression patterns in all tumor types with high ESR2 expression as a positive prognostic factor with regard to OS or DFS." (PMID 39201394, 2024).
cancer (11 papers, 2018 to 2024). A tumor composed of atypical neoplastic, often pleomorphic cells that invade other tissues. "The enrichments among hotspots in the protein-coding genes as well as in the splice-sites and promoters can be explained by known driver hotspots, whereas the enrichment among enhancer hotspots partly was caused by an SNV hotspot in an enhancer for POU2AF1 that may be a non-coding cancer driver." (PMID 33986299, 2021). "Expression of IRS1 and POU2AF1 in MM cell lines extracted from the Cancer Cell Line Encyclopedia and the pan cancer proteomic map46 is highly correlated with genetic dependency." (PMID 38942927, 2024). "Furthermore, we find an excess of hotspots associated with cancer genes compared to other genes in various regions, including enhancers, where an SNV hotspot in an enhancer for the oncogene POU2AF1 comes up with signs of positive selection in multiple of our analyses." (PMID 33986299, 2021). "The remaining eight target genes (CFL1, FNBP4, NDUFB3, OCIAD2, PLIN3, POU2AF1, RAC1, TMEM141) presented a combined influence in five or fewer cancer types." (PMID 39201394, 2024). "Among most of the descendant cancer cells, more cancer-related changes were obtained, such as in CCNE1, POU2AF1, and KRAS." (PMID 35951662, 2022). "Using data from the DepMap project, we confirmedthat POU2AF1 is selectively indispensable for the growth of DLBCL and multiplemyeloma (MM) cells but not essential in other cancer types." (PMID 39029462, 2024).
infection (6 papers, 2008 to 2025). The state of being infected such as from the introduction of a foreign agent such as serum, vaccine, antigenic substance or organism. "Also the expression of transcription factors was significantly modified by HHV-6A/6B infection, with an early increase of ATF3, JUN and FOXA2 by both species, whereas HHV-6A specifically induced a 15-fold decrease of POU2AF1, and HHV-6B an increase of FOXO1 and a decrease of ESR1." (PMID 29163428, 2017).
POU2AF1 also shares sentences with these, for which no sentence is quoted: B cell lymphoma (6 papers); autoimmune disease (4); asthma (2); B-cell neoplasm (2); hematologic malignancies (2); melanoma (2); periodontitis (2); Type 1 diabetes (2); viral infection (2); abdominal aortic aneurysm (1); classic Hodgkin lymphoma (1); colorectal cancer (1); gastrointestinal stromal tumor (1); Glucose intolerance (1); Granuloma (1); heart failure (1); hypercortisolemia (1); Immunodeficiency (1); Insulin resistance (1); iron deficiency (1); liver cancer (1); Lynch syndrome (1); metastatic tumors (1); neuroblastoma (1); primary biliary cholangitis (1); primary effusion lymphoma (1); prostate carcinoma (1); rectal cancer (1); systemic lupus erythematosus (1).